EGFR (epidermal growth factor receptor)
Diseases named in the same sentence as EGFR in open-access papers (continued):
Sharing a sentence is not in itself a finding about the gene and the disease.
tumor (continued). "They found that high expression levels of ERBB2 occurred in spheres showing hyperactive PI3K/AKT pathway and proved that triple targeting of ERBB2, MEK and PI3K induces CSC death and regression of anti-EGFR-resistant tumor xenografts, including those carrying KRAS and PIK3CA mutation." (PMID 35582524, 2022). "SDF-1α secreting cells such as cancer-associated fibroblasts and tumor endothelial cells may substitute for interrupted EGFR signaling by paracrine signaling via CXCR418." (PMID 35039644, 2022). "CfDNA in the plasma has a high specificity in detecting EGFR mutations but is associated with a low sensitivity; this is because very small amounts of cfDNA exist in the blood as cfDNA is released from tumor cells only during cell death and is rapidly cleared from the circulation." (PMID 35681723, 2022). "Heightened EGFR/K-RAS/MAPK activation has multiple deleterious effects on the tumor/tumor microenvironment (TME), which is associated with decreased tumor-infiltrating lymphocytes (TIL) detection in TNBC and is correlated with increased metastases and poor prognosis in breast cancer." (PMID 36176751, 2022). "EGFR inhibition as monotherapy for metastatic cSCC has had moderate success, even though EGFR is often overexpressed in cSCC, with one study showing an association with EGFR levels and lymph node progression and tumor cell proliferation." (PMID 35480116, 2022). "The aberrant activation of EGFR has been implicated in tumor growth." (PMID 35563563, 2022). "The outcome of BR19 might be too short to evaluate the adjuvant TKI usage, and the number of patients with EGFR mutations was low at only 4% (15 cases of tumor) in the cohort." (PMID 35360423, 2022). "Tumor re-biopsy can be omitted in patients with positive EGFR mutations by liquid biopsy at PD." (PMID 36192767, 2022). "Furthermore, exact primary tumor location is associated with a rather continuous increase in anti-EGFR antibody efficacy from proximal to distal segments of the colorectum in patients with RAS/BRAF wild-type tumors." (PMID 35158793, 2022). "Blood-based testing compared with tissue testing for EGFR activating mutations had a positive percent agreement of 74.5% and a negative percent agreement of 90.5%, with a 78% overall percentage agreement between matched plasma and tumor tissue samples." (PMID 35482671, 2022). "In brief, older patients, male patients, larger tumor size, solid, or micropapillary components were associated with a higher probability of abnormal CEA level, whereas female patients, EGFR mutation, and high grade of tumor differentiation were associated with a lower risk of aberrant level of CEA." (PMID 35289087, 2022). "EGFR-activating mutations are highly associated with tumor responses to EGFR-TKIs." (PMID 36232650, 2022). "In addition, the expression of tumor drug resistance genes, EGFR, and MET were remarkably higher among the high-risk group than low-risk patients, positively related to risk score." (PMID 36497225, 2022). "For 11C-erlotinib and 18F-afatinib, studies have shown that EGFR mutation positive patients can be identified and that tumor response to treatment using the corresponding EGFR TKI could be predicted using PET biomarkers." (PMID 36313723, 2022). "Besides, a growing body of research indicated that EGFR mutations are closely related to tumor onset, while increased copy number is associated with tumor progression." (PMID 36528578, 2022). "However, the signalling cascades associated with EGFR activation and tumour cell growth and invasion are complex and have yet to be fully elucidated." (PMID 36497413, 2022). "Furthermore, miR4429 was found to be related to tumor size, EGFR mutation, lymph node metastasis, and TNM stage in NSCLC patients by the Chi-square test." (PMID 35167433, 2022).
tumor (continued). "In the early stages of our study, the application of chemotherapy or EGFR-TKIs for EGFR mutation patients was found to be an increase in the expression of PD-L1 in the tumor cell surface, and the PD-L1 was significantly reduced after the treatment of the anti-PD-1." (PMID 36185620, 2022). "The mTOR mutation E2419K also contributes to tumor resistance to EGFR-TKI." (PMID 35684449, 2022). "Nevertheless, the off-target mechanism of resistance may be more relevant in first-line osimertinib than in later-line treatment, in which tumour cells have previously displayed dependence on EGFR through T790M mutation." (PMID 35805940, 2022). "Moreover, high B7-H3 expression was associated with tumor grading, wild-type EGFR status, and staging." (PMID 36555714, 2022). "Additionally, the rate of discordance of EGFR mutation status between primary lung tumors and paired BMs was 15.4% in the 52 patients who underwent EGFR gene testing in both the primary tumor and the BM." (PMID 35912248, 2022). "Tumours with EGFR activation mutations might entirely depend on the activity of EGFR to promote the signalling pathway." (PMID 35745802, 2022). "The pretreatment presence of tumor cells clones harboring EGFR-Thr790Met mutation may have been underestimated because of the limit of detection (LOD) of the conventional EGFR testing methods." (PMID 35955661, 2022). "Furthermore, the binding of EGFR and EphA2 to each other correlates to Ephexin1 levels, and interactions between EGFR and EphA2 are associated with an increasingly poor tumor tissue grade." (PMID 35668076, 2022). "Patients previously tested and found to have actionable tumor biomarkers other than EGFR mutations were under-represented in the cohort; therefore, the potential benefit of biomarker testing after such treatments could not be clearly established." (PMID 35877242, 2022). "In the first case, tumour cell proliferation remains directly linked to EGFR signalling." (PMID 35805940, 2022). "The different resistant mutations may occur at a small clone of tumor cells, and clonal evolution may develop during the EGFR-TKIs treatment process." (PMID 35309168, 2022). "Tumor cells in some patients might evolve with multiple mutations including T790M, C797S, plus the original EGFR-TKI-sensitive mutations (SM: sensitive mutation, e.g., L858R or Del19 E746_A750)." (PMID 34903832, 2021). "Similarly, our data suggested that patients carrying uncommon EGFR mutations with concurrent tumor-suppressor genes aberrations are associated with inferior outcomes on EGFR-TKIs therapy." (PMID 34513661, 2021). "In addition to the Cobas EGFR Mutation Test v2, the Therascreen EGFR RGQ PCR Kit (Qiagen, Valencia, CA) has been approved by the European agency to detect EGFR mutations when tumor tissue is insufficient." (PMID 34074295, 2021). "Since parental H1975 cells expressed EGFR receptor with activating point mutation L858R and secondary T790M mutation, we tested whether tumor spheres maintained the same EGFR mutations." (PMID 33922104, 2021). "EGFR mutation status were most commonly seen in exons 19 and 21 for both primary tumour and LCBM." (PMID 35201504, 2021). "Mutations and excess phenotypes or mutations of EGFR are associated with aggressive tumor behavior." (PMID 34869005, 2021). "Additionally, tumor cells with a low EGFR expression have low tumor metastatic risk and better survival rates in CRC patients." (PMID 33827580, 2021). "Each EV sample was tested for EGFR mutations matching the tumor biopsy result." (PMID 34692681, 2021). "Moreover, the study observed an association between EGFR status and depth of tumor invasion and tumor size." (PMID 34638601, 2021). "Furthermore, the incidence of EGFR mutations appears to be dependent on tumor histological type, gender, smoking history, and ethnic background." (PMID 33906297, 2021).
tumor (continued). "Finally, we observed HER3 upregulation in EGFR-mutated NSCLC cell lines treated with EGFR-TKIs and in tumor samples obtained from patients with EGFR-mutated NSCLC treated with EGFR-TKIs." (PMID 33801379, 2021). "EGFR-mutated tumours also tended to have peripheral lesions (p = 0.035) and GGOs (p < 0.001), especially mixed GGOs (mGGOs) (p = 0.045), well-defined margins (p = 0.022), air bronchograms (p < 0.001), pleural retraction (p < 0.001) and no lymphadenopathy (p = 0.001)." (PMID 33707479, 2021). "Previous studies demonstrated underlying associations between the EGFR mutation status and intra-tumor heterogeneity on computed tomography (CT) images quantified using conventional radiomic features such as shape-, original image (OI)-, wavelet-decomposition (WD)-, and deep learning-based features." (PMID 33428651, 2021). "Similarly, tumor patients with EGFR mutations demonstrated worse prognosis compared with patients without EGFR mutations (P < 0.0001)." (PMID 33959491, 2021). "Therefore, it is crucial to predict EGFR gene mutation for patients who cannot undergo genetic testing to determine EGFR mutation status by using indicators and methods such as clinicopathological features, tumor markers, and fluid biopsy." (PMID 35049681, 2021). "The indicators, including clinicopathological features, serum tumor markers, liquid biopsy, and others which are less invasive, economical, easier to obtain, and monitored in real-time, have been proven to be associated with EGFR gene mutation." (PMID 35049681, 2021). "Therefore, we believe that EGFR mutation can be a good supplement to histological, imaging and morphological evidence of tumor, so as to better distinguish multiple primary lesions from metastatic lesions and provide patients with a more accurate staging." (PMID 35096585, 2021). "Compared with the CC genotype, at least G genotype (CG and GG) allele on WWOX rs3764340 also enhanced the risk of the tumor status, including the size of the primary tumor and the invasion of adjacent tissues in patients with EGFR L858R mutation (OR = 3.681, 95% CI = 1.259–10.757, p = 0.014)." (PMID 34948746, 2021). "Thus, tests to confirm the T790M mutation have become a mandatory procedure using either tumor rebiopsy or plasma assays after progression following first‐line EGFR‐TKI treatment." (PMID 33270375, 2021). "Hypothesizing that EGFR mutations alter tumor-immune interactions, we compare tumor-infiltrating lymphocytes between EGFR mutant (EGFR-MT) and wild type (EGFR-WT) tumors through single-cell transcriptomic analysis." (PMID 34663810, 2021). "Therefore, it was further validated that it is a reasonable time to start primary tumour radiotherapy at 40 days after EGFR-TKI treatment in patients with EGFR-positive mutations." (PMID 34631535, 2021). "Loss of EGFR or HIF1α abrogates Th9 cell differentiation and suppresses their anti-tumor functions." (PMID 34075041, 2021). "However, plasma EGFR mutations were detected only in 76.7% of the patients with EGFR mutations, confirmed from tumor tissues." (PMID 34074295, 2021). "Circulating tumor DNA (ctDNA) is the most commonly analyzed DNA to detect EGFR mutations in NSCLC." (PMID 33435996, 2021). "Clinical studies also have confirmed that reversing the TIME might reduce tumor-induced immunosuppression in patients with a mutated EGFR." (PMID 34136375, 2021). "First- and second-generation TKIs, such as gefitinib, erlotinib, afatinib, and dacomitinib, are used continuously until evidence of tumor resistance, which happen frequently by the selection of a secondary mutation in the kinase domain of the EGFR, particularly T790M." (PMID 34211836, 2021). "EGFR overexpression has been associated with larger tumor size and poor clinical outcome." (PMID 34899753, 2021). "SPP1 expression was higher in EGFR-mutated tumor samples than in wild-type samples (P = 0.017)." (PMID 34178613, 2021).
tumor (continued). "linked the EGFR expression with MMP-9 upregulation in tumor cells in vitro in NSCLC patients." (PMID 34976811, 2021). "However, anti-EGFR therapies are often affected by tumor cell mutation associated with resistance based on alterations in EGFR-driven signaling systems." (PMID 33827580, 2021). "In addition, the evidence shown in the present study indicates that the trajectory of increasing EGFR mutation levels (MAF) is an important signal that a patient's tumor burden is increasing." (PMID 34296539, 2021). "Moreover, univariate analysis of patients with EGFR mutations in ctDNA identified the L858R mutation in tumor tissue or in ctDNA as a marker of shorter OS (hazard ratio, 2.70, P < 0.001) and PFS (hazard ratio, 2.04, P = 0.008)." (PMID 33969622, 2021). "Additionally, four patients underwent tumor re-biopsies after disease progression, including two patients with EGFR and one KRAS mutation." (PMID 34884672, 2021). "Importantly, post-CAR T-treated tumor specimens showed the continued presence of EGFR amplification and missense mutations, despite the decrease in EGFRvIII target antigen." (PMID 34568006, 2021). "A nude murine PC9 xenograft tumor model was constructed to assess whether the loss or rescue of LANCL2 expression affects the growth of EGFR-mutant LUAD xenograft tumors in vivo." (PMID 33568630, 2021). "Interestingly, in G2 and G3 patients who have relatively early onset age, the patients with EGFR mutation had tumour occurrence at old age as well as G4." (PMID 34205437, 2021). "In addition, Balb/c athymic nude mice subcutaneously injected with HCT116 or EGFR-knockout CT116 cells also revealed that depletion of EGFR in HCT116 cells was associated with reduced tumor growth." (PMID 33466394, 2021). "This could additionally be beneficial for preventing needless tumor biopsies to test for EGFR mutation." (PMID 33855679, 2021). "At present, a few subgroups of clinical trials have reported the comparison between immune checkpoint inhibitors and chemotherapy in patients with different molecular characteristics, such as PD-L1 protein expression, EGFR gene expression, tumor mutational burden (TMB), and so on." (PMID 33725808, 2021). "Furthermore, in cases with suboptimal tissue available for DNA amplification, either due to low tumor contents or decalcified tissue from bone metastasis, immunohistochemistry can be performed as a screening tool for the detection of the EGFR gene mutations." (PMID 34181354, 2021). "In addition, EGFR mutation was found in 47.5% CNPE supernatant and 32.5% matched tumor biopsy specimens, indicating that CNPE specimens were better than tumor tissue specimens in detecting EGFR mutations." (PMID 35049681, 2021). "However, 30–40% of patients with GBM carry a mutant self‐active variant of EGFR, named EGFRvIII, which increases tumor aggressiveness." (PMID 33959279, 2021). "In addition, the present study showed a favorable ORR and PFS with afatinib similar to that observed in previous trials assessing it as the first‐line treatment of EGFR‐mutated NSCLC based on tumor genotyping." (PMID 33270375, 2021). "SHP-1 was negatively associated with EGFR in both human breast cell lines and tumor specimens." (PMID 34591414, 2021). "Since EGFR promotes tumorigenesis and progression by downstream signalling pathways, causing poor outcomes in NPC patients, EGFR-targeted drugs could be considered a newly developed anti-tumor drug." (PMID 34578147, 2021). "To clarify the biological characteristics of high-RS populations, we performed GSEA on the gene expression profile of EGFR-WT NSCLC patients using the tumor-related HALLMARK pathway gene set and the classic Kyoto Encyclopedia of Genes and Genomes (KEGG) pathway gene set." (PMID 33763356, 2021). "Consequently, the proportions of patients with data available on tumor histology, EGFR mutation type, response and TTF were relatively low." (PMID 33783657, 2021).
tumor (continued). "The reduction of glucose uptake has been implicated in the anti-tumor activity of EGFR TKIs." (PMID 34155348, 2021). "Furthermore, EGFR expression, genomic amplification, and truncation were each associated with differential prognosis and therapeutic response in tumor cell growth and angiogenesis." (PMID 33917013, 2021). "The poor clinical response rate of patients with EGFR-mutant NSCLC to anti-PD-1/PD-L1 treatment mechanisms is still unclear but may be associated with the low tumor mutational burden (TMB) of those cancers, leading to weak immunogenicity." (PMID 34638411, 2021). "In recent years, studies have shown that EGFR mutations may exert an anti-tumour immune response by affecting the TME." (PMID 34631565, 2021). "High Amphiregulin, PTEN and low P21 expression levels were associated with low tumor grade (p= 0.038 and 0.025 respectively), better response to anti-EGFR treatment (p <0.001), and favorable outcome {progression-free survival (PFS) and overall survival (OS)} (p <0.05)." (PMID 33906293, 2021). "The tumor initially showed a complex EGFR V774_C775insLM mutation." (PMID 33048186, 2021). "Furthermore, miR-184 and miR-197 were up-regulated in LADC tumor tissue patients, who harbor EGFR mutations with brain metastasis, indicating these miRNAs as novel biomarkers differentiating the risk of brain metastasis." (PMID 34830377, 2021). "Analysis of clinically relevant mutations revealed an epidermal growth factor receptor (EGFR) mutation for the donor of LCSCs_a as well as tumor tissue of the donor of LCSCs_c showed mutations in the genes for the KRAS proto-oncogene (KRAS) and serine/threonine kinase 11 (STK11)." (PMID 33800955, 2021). "By clarifying this association, it may be possible to identify NSCLC patients with a high risk of postoperative recurrence based on the information of the PD-L1 expression and EGFR mutations within the resected tumor." (PMID 34471191, 2021). "However, previous works revealed that EGFR-mutated NSCLCs have lower PD-L1 expression and a low tumor mutational burden, leading to weak immunogenicity and, thus, a weak response to ICIs." (PMID 34440926, 2021). "The EGFR mutation status was identical to that of FFPE sections of the tumor specimen." (PMID 33757469, 2021). "Positional cloning of the tumor gene revealed that a mutated epidermal growth factor receptor gene (egfr) named xmrk (Xiphophorus melanoma receptor kinase), which originated from tandem duplication of the Xiphophorus EGFR, is responsible for the tumorigenesis." (PMID 33231252, 2021). "At the genomic level, the tumor mutation burden was higher in EGFR wildtype patients." (PMID 34055528, 2021). "We aimed to prove the worth of liquid biopsy as plasma but also as urine and exhaled breath condensate (EBC) as the best surrogate to tumor tissue as well as to explore the molecular mechanisms that underlying the resistance to second-line osimertinib in advanced EGFR mutated NSCLC." (PMID 34771566, 2021). "Although tyrosine kinase inhibitors (TKIs) that target mutant EGFR in NSCLC have been successful in controlling tumor growth, they may also invariably induce acquired resistance due to EGFR mutations." (PMID 34102455, 2021). "Furthermore, systemic immune dysregulation was correlated with multiple clinical features, such as sex, age, smoking history, pathological type, tumor stage, surgical approach, tumor differentiation, and epidermal growth factor receptor (EGFR) mutation." (PMID 35116020, 2021). "To assess whether PHLPP expression associate with resistance to EGFR-TKI in clinical, we detected PHLPP expression levels in tumor samples using IHC technology, these pre- and post-development samples were from patients who carry EGFR common mutations." (PMID 34168988, 2021).